TLR9 (toll like receptor 9)
Diseases named in the same sentence as TLR9 in open-access papers (continued):
Sharing a sentence is not in itself a finding about the gene and the disease.
lupus (continued). "Another study revealed a higher level of TLR9 transcripts in lupus nephritis biopsies and a significant genotypic and allelic association between rs352140 and both SLE and lupus nephritis." (PMID 37139337, 2023). "For instance, patients with systemic sclerosis and/or systemic lupus erythematosus (SLE) were demonstrated to have deficient B cell activation response after Toll-like receptor (TLR)-9 stimulation." (PMID 36405752, 2022). "Therefore, loss of TLR9 or AhR in lupus prone mice exacerbated disease." (PMID 31354738, 2019). "The induction of the IFN signature could be the result of an inheritable disease risk factor, and it could also be amplified by the autoimmune activation of endosomal TLR7 and TLR9 by immune complexes containing lupus-associated autoantibodies and self-nucleic acids." (PMID 28410407, 2017). "The current study compared B cells from healthy donors and SLE patients for production of cytokines and growth factors, proliferation and expression of activation markers upon TLR9 stimulation taking the underlying lupus activity into consideration." (PMID 25385499, 2014). "We will compare and contrast the roles of TLR7 and TLR9 in lupus and SjD, with a focus on the importance of B cell activation in disease." (PMID 42112403, 2026). "In lupus-prone mice, TLR9 is essential for the generation of DNA autoantibodies, while TLR7 is crucial for generating antibodies to RNA-containing antigens." (PMID 40584714, 2025). "PLD4 loss-of-function mutations in patients with systemic lupus erythematosus leads to excessive activation of TLR7 and TLR9." (PMID 40931063, 2025). "Endosomal toll-like receptors (TLRs) TLR7, TLR8, and TLR9 play an important role in systemic lupus erythematosus (SLE) pathogenesis." (PMID 39858436, 2025). "Although generally considered homologous, they paradoxically have opposing effects on lupus: TLR7 exacerbates the disease while TLR9 protects from it How they mediate opposing effects in autoimmunity remains undetermined." (PMID 40794441, 2025). "In lupus‐prone mice, a deficiency in NADPH oxidase has been shown to increase TLR7 and TLR9 signaling, resulting in increased autoantibody production, which exacerbates lupus risk." (PMID 40491969, 2025). "Finally, the TIR domains of TLR7 and TLR9 — which share only 42% sequence identity — could have fundamentally different properties that could encode meaningfully different downstream signaling and, thus, disease outcomes in the context of lupus." (PMID 40794441, 2025). "The role of TLR9 signaling is MyD88-independent in lupus, while the MyD88-mediated proinflammatory signaling promotes disease." (PMID 39960645, 2025). "Tlr779 mice — in which the Tlr7 TIR domain was replaced with the Tlr9 TIR domain — showed disease amelioration when compared with WT Tlr7 counterparts in the lupus-prone MRL/lpr Tlr9–/– background." (PMID 41178711, 2025). "“Toll-like receptor 7 and TLR9 dictate autoantibody specificity and have opposing inflammatory and regulatory roles in a murine model of lupus” by SR Christensen is the reference with the second largest citation count of 35 in this cluster." (PMID 40584714, 2025). "Toll-like receptor 9 (TLR9) recognizes self-DNA and plays intricate roles in systemic lupus erythematosus (SLE)." (PMID 38169466, 2024). "It has been demonstrated that B-cell-specific knockout of Tlr7 is enough to ameliorate disease in lupus-prone mice, while B-cell-specific knockout of Tlr9 exacerbates disease." (PMID 38791389, 2024). "Overexpression of TLR7 can induce systemic autoimmunity in normal mice, while deletion of TLR7 can significantly alleviate the pathogenesis of lupus in mice; TLR9 deletion significantly exacerbates the pathogenesis of lupus in mice." (PMID 38429401, 2024). "Since Tlr9 activation diminishes Tlr7-mediated pathology in the context of lupus, we next performed flow cytometry to assess expression of Tlr9 in Tlr7-deficient males and females." (PMID 39310226, 2024).
lupus (continued). "In 2015, it was reported that mice with null TLR9 showed more severe lupus than control mice in which greater immunoglobulin deposits and more severe LN were found." (PMID 39000140, 2024). "We focused our analyses on the B cell compartment, as B cell-intrinsic Tlr7 mediates lupus pathogenesis and overexpression of Tlr9 in B cells protects against lupus." (PMID 39310226, 2024). "Recent research has further demonstrated that inhibitors like TAC5 can selectively target endosomal TLRs (TLR3, TLR7, TLR8, and TLR9) to modulate immune responses and potentially treat autoimmune diseases like psoriasis and systemic lupus erythematosus." (PMID 38732254, 2024). "While TLR9 may recognize self-DNA for anti-inflammatory effects during infection and for homeostasis, TLR9 stimulation for some reason causes the production of antinuclear antibodies in the pathology of autoimmune diseases, such as systemic lupus erythematosus (SLE)." (PMID 38659975, 2024). "But in mice, numerous studies have shown that TLR7 signaling is central to the lupus phenotype, whereas knockout of TLR9 alone has only subtle effects on autoantibody specificity or exacerbated disease." (PMID 37555846, 2023). "Recent genetic studies of TLR9 functions in lupus uncovered complex regulatory and unclear proinflammatory functions of TLR9." (PMID 36875095, 2023). "The capacity of B cells from lupus patients to produce IL-10 cytokines upon TLR9 engagement becomes less efficient with increasing disease activity." (PMID 37771588, 2023). "Despite the pathogenic role of TLR7, and despite that TLR7 and TLR9 are highly homologous and are thought to signal in similar ways, TLR9 plays a dominant protective role, while TLR7 is pathogenic in lupus." (PMID 37606042, 2023). "This implicates TLR7 and TLR9 signaling in B cells, contributing to autoreactive B cell activation in various lupus mouse models." (PMID 37841260, 2023). "Rommler found that agonists of TLR7 or TLR9 activated pDCs in lupus patients, even in healthy people, to induce a large amount of IFNα and immune overactivation." (PMID 36555668, 2022). "In this study, its immunosuppressive effect as a TLR7 or TLR9 antagonist was investigated in a lupus mouse model." (PMID 36555668, 2022). "TLR9-deficient mice have increased immune activation, accelerated lupus nephritis and mortality, whereas TLR7-deficient lupus-prone mice are protected from autoimmune disease; and renal disease was ameliorated as well." (PMID 36405752, 2022). "The production of autoantibodies relied on TLR9 signals in the spontaneous lupus mouse model, but TLR9 deletion aggravated the mortality and renal injury of TLR9−/− in lupus-susceptible mice." (PMID 36555668, 2022). "The R-to-H change in NCF1 led to decreased phospholipid-binding affinity, less endosomal localization, and acidified endosomal pH, followed by increased cleavage of TLR7 and TLR9, resulting in excessive activation of pDCs and aggravated lupus progression." (PMID 35788118, 2022). "It will be interesting to look at role of TLR9‐mediated functions in the context of disease pathology in diseases like systemic lupus erythematosus, where anti‐DNA responses constitute a central part of disease pathology." (PMID 37406035, 2022). "In lupus, DNA-containing ICs released upon NETosis are able to activate TLR9 in pDCs and induce the production of IFN-α." (PMID 36359340, 2022). "The mystery of why deletion of TLR9 in lupus prone mice leads to exacerbation of SLE was resolved by studying the correlation between TLR7 and TLR9." (PMID 36389822, 2022). "TLR9, which has long been studied as an important nucleic acid sensor in lupus, when entirely deleted in preclinical mouse models (similar MRL genetic background), also led to paradoxical exacerbation of lupus disease activity and decreased survival." (PMID 35693769, 2022).
lupus (continued). "Overexpression of TLR9 in B cells ameliorates nephritis in lupus mice, further indicating a protective role of B-cell-intrinsic TLR9 signaling in autoimmunity." (PMID 36220996, 2022). "Innate stimulation, such as through TLR7 and TLR9, is known to drive activation of autoreactive B cells in systemic lupus erythematosus." (PMID 34234784, 2021). "The single-stranded DNA (ssDNA) sensor, TLR9, also promotes lupus nephritis in lupus-prone Tnip1-/- mice." (PMID 34868046, 2021). "In contrast, the association between clinical manifestations and TLR7, TLR8 and TLR9 polymorphisms is clear and the involvement of the endosomal TLRs, mainly TLR7, in lupus is backed up by several studies." (PMID 34572504, 2021). "Systemic lupus erythematosus (SLE) development is classically linked to endosomal toll like receptor (TLR) 7 and TLR9 nucleic acid sensors engagement and the role of the cGAS/STING pathway remains elusive." (PMID 34659260, 2021). "A Japanese study on systemic lupus erythematosus (SLE) showed that a C allele at position −1486 has the ability to downregulate TLR9 expression, indicating that C allele carriers may be susceptible to diseases associated with the TLR9 gene." (PMID 33777838, 2021). "The case for TLR 9 is actually more complex, because in early stages, TLR9 actually protects against lupus, possibly by promoting tolerance in APC, B cells and helping Treg generation." (PMID 33936042, 2021). "Expression of major members of Type I IFN genes themselves, as well as type I IFN induced genes (ISG) were markedly reduced by histone peptide epitopes in TLR9-stimulated PBMC of lupus patients." (PMID 33936042, 2021). "Irf7 is induced downstream of both Toll-like receptor 7 (TLR7), TLR9, and type I interferon receptor ligation, all key molecules in mouse lupus pathogenesis." (PMID 34220829, 2021). "Low expression of TLR9 due to single nucleotide polymorphisms would increase SLE susceptibility in humans, and deletion of TLR8 and TLR9 would accelerate lupus development in mice." (PMID 35126357, 2021). "Various oligonucleotides that mimic TLR ligands (for TLR7, TLR8, TLR9) have been synthesized and are prospective therapeutics for lupus." (PMID 34572504, 2021). "In summary, we investigated the effects of chronic exposure to a human-relevant dose of 17α-ethinyl estradiol on kidney disease and response to ssRNA viral (TLR7) or bacterial (TLR9) challenge in a mouse model of systemic lupus erythematosus." (PMID 32251357, 2020). "STING has been reported not only to function as a DNA sensor but also to negatively regulate TLR7 and TLR9 responses in lupus-prone mice." (PMID 33093516, 2020). "On the other hand, aberrant activations of TLR7 and TLR9 have been implicated in type I IFN-related autoimmune diseases, such as systemic lupus erythematosus (SLE), which is characterized by the presence of autoantibodies against nucleic acids." (PMID 32708595, 2020). "Although TLR9 signaling contributes to the development of lupus nephritis, enhanced TLR9 signaling prevents severe manifestations and defective TLR9 expression promotes inflammation in murine lupus." (PMID 33224145, 2020). "Recently, another laboratory reported that crossing ABIN1 KO mice to either TLR7 KO mice or TLR9 KO mice had little effect on autoimmunity or glomerulonephritis and that crossing to TLR7/TLR9 double KO mice was required to prevent these hallmarks of lupus." (PMID 31694920, 2019). "Previously, we have shown that hAAT treatment inhibited BMDC activation and cytokine secretion upon stimulation with TLR4 or TLR9 agonists in B6 and lupus-prone B6." (PMID 31470606, 2019). "In contrast, TLR7 was needed for the organomegaly that was observed in TLR9−/− mice, indicating that TLR7 and TLR9 worked together to control clinical symptoms and autoantibody production in lupus." (PMID 30103522, 2018).
lupus (continued). "Nonetheless, the effect of rAAV8-CB-hAAT vector DNA on TLR9 activation should be further investigated in additional lupus models before translating these results into clinical applications." (PMID 30547047, 2018). "We selected CpG, a TLR9 agonist, to activate DCs since the TLR9 pathway plays a pivotal role in lupus pathogenesis." (PMID 30547047, 2018). "Our observations provide new insights about the MZ B cell translocation in lupus patients as well as the dichotomy of TLR9 and TLR7 signals in the pathogenesis of lupus." (PMID 30286201, 2018). "It was also demonstrated that Gal-9 inhibits TLR7/TLR9-mediated lupus in mouse models by modulating plasmacytoid DCs and B cells, and protects kidney from immune complex-induced damage." (PMID 30687334, 2018). "E2 also strengthens the amplification of the IFN signature induced by TLR7 and TLR9 stimulation in lupus cDCs." (PMID 29850618, 2018). "We, and others, have also shown that stimulation via TLR7 and TLR9 is important in the induction of Type I IFNs in lupus." (PMID 29456540, 2018). "Despite the differences between model systems, our observations provided some explanation of the protective role of TLR9 in murine lupus." (PMID 30286201, 2018). "Several murine studies have highlighted the importance of TLR7, and that TLR9 surprisingly provides protection, in lupus pathogenesis." (PMID 30210502, 2018). "TLR9 inhibitors have been developed for a variety of diseases such as systemic lupus erythematosus (SLE), and block death in the mouse model of cerebral malaria." (PMID 29495555, 2018). "Although generalization of our observations is limited by the nature of transgenic B cells, their different sensitivities to apoptotic cell associated antigens is consistent with the dichotomy of the TLR9 and TLR7 pathways observed in murine lupus." (PMID 30286201, 2018). "TLR9 plays a protective role in lupus and emerging work suggests that TLR9 activation also ameliorates disease in SS." (PMID 30671484, 2018). "Prior exposure of pDCs to either a TLR9 agonist or lupus serum reduces IFN-α production by these cells." (PMID 29052537, 2017). "Several lines of evidence have revealed inappropriate activations of TLR7, TLR8, and TLR9 in systemic lupus erythematosus (SLE) and several other autoimmune diseases." (PMID 28061847, 2017). "As previously reported, lupus pDCs produced lower levels of IFN-α after stimulation with a TLR9 agonist." (PMID 29052537, 2017). "The exacerbation of disease in Tlr9-/- MRL.Faslpr was dependent on both Tlr7 and Ifnar1, suggesting that intact Tlr9 inhibits a proinflammatory signaling axis on the lupus-prone genetic background." (PMID 28278279, 2017). "The decreased production of IFN-α by lupus pDCs upon TLR9 activation has been reported by other groups." (PMID 29052537, 2017). "In addition to establishing that Tlr9 regulates lupus-like disease in a fully polygenic lupus model independently of Fas-deficiency, we revealed additional features regulated by Tlr9 that may have been obscured by the global immune disregulation mediated by the Fas mutation." (PMID 28278279, 2017). "TLR9 is triggered by the main autoantigen in lupus, double-stranded DNA (dsDNA), and by the immune complexes carrying DNA and leads to DC hyperactivation and stimulation of autoreactive B cells." (PMID 28811679, 2017). "TLR9 plays crucial roles in the pathogenesis of glomerulonephritis, though some recent studies report that TLR9 can be protective in systemic lupus erythematosus (SLE) patients." (PMID 28356164, 2017). "When Yaa are combined with systemic lupus erythematosus (SLE) mice and the Tlr9 gene knocked out, mice have increased RNA-associated antibodies, exacerbated clinical symptoms, and accelerated mortality." (PMID 28751890, 2017). "TLR9 rather ameliorates TLR7-dependent development of lupus-like disease by competing endosomal transport with TLR724." (PMID 28408984, 2017).
lupus (continued). "Of note, the TLR9 pathway is particularly important in systemic lupus erythematosus (SLE), where autoantibody production and cytokine production by PDCs are crucial." (PMID 27090981, 2016). "TLR9 activation plays an important role in inducing anti-chromatin and anti-DNA autoantibody production in murine lupus." (PMID 27232337, 2016). "Studies have shown that the pathogenic role of TLR7 in lupus-prone mice is partially dependent on IFNα induction, and TLR9 on the contrary can regulate lupus progression by suppressing TLR7 signaling." (PMID 27034965, 2016). "DCs play a crucial role in the pathogenesis of lupus through IFN-α production upon TLR7-/TLR9 stimulation." (PMID 27232337, 2016). "The aim of this study was to analyze the pDC phenotype and its IFNα-producing ability by following Tlr7 and Tlr9 stimulation in different lupus-prone mouse strains." (PMID 26879679, 2016). "In the tape-stripping model, depletion of pDCs protected NZB/W F1 mice from developing chronic skin lesions and so did the treatment of TLR7 and TLR9 inhibitors, suggesting that TLR7 and TLR9 signaling is important for lupus development." (PMID 27509492, 2016). "Antimalarial drugs such as hydroxychloroquine which act as a TLR7, TLR8 and TLR9 antagonist are used for the treatments of rheumatoid arthritis and systemic lupus erythematosus." (PMID 26226614, 2015). "Subsequent researches demonstrated that activation of TLR9 accelerated renal disease in a lupus mouse model, MRL/MpJ-Faslpr/J mice (common name MRL-lpr, mouse model that has spontaneous mutation of FAS gene and is prone to SLE)." (PMID 25927578, 2015). "In particular, the increased level of TLR9 in B cells is highly correlated with organ damage in lupus patients." (PMID 26068236, 2015). "TLR7 and TLR9 expression levels are significantly elevated in glomerulonephritis in systemic lupus erythematosus." (PMID 24810370, 2014). "Dynavax Technologies in partnership with GlaxoSmithKline have consequently developed DV1179, a bifunctional inhibitor of TLR7 and TLR9, which has been shown to reverse glucocorticoid resistance in both human cells and animal models of lupus." (PMID 24474949, 2014). "The current data are consistent with an exhaustion of B cells, or an induction of TLR-tolerance post-activation (by diminished TLR9 expression) depending on lupus disease activity." (PMID 25385499, 2014). "Although TLR9 provides protection against lupus in mice, deleting it lowers anti-dsDNA antibody production." (PMID 25147296, 2014). "TLR7/8 and TLR9 signaling pathways have been extensively studied in systemic lupus erythematosus (SLE) as possible mediators of disease." (PMID 25485543, 2014). "More recently it has been shown that exogenously administered agonists of TLR3, TLR7 and TLR9 can exacerbate murine lupus." (PMID 24086313, 2013). "Signal transduction pathways involving TLR9 and the BCR have been linked to the hyper B cell responses in autoimmune diseases such as Systemic lupus erythematosus (SLE)." (PMID 23967355, 2013). "Recognition of self-nucleic acids by TLR7 and TLR9 on plasmacytoid dendritic cells is considered to be a key steps in IFN production in lupus and correlated with the severity of disease." (PMID 22952664, 2012). "The DNA-binding TLR9 has also been heavily studied in connection with murine lupus in MRLlpr/lpr strains." (PMID 21860649, 2012). "Increased tubular expression of TLR-9 correlates with proteinuria and tubulo-interstitial injury in lupus patients, whereas increased glomerular TLR-9 expression is associated with a higher activity index." (PMID 22761629, 2012). "Inhibition of TLR-9 signaling in lupus-prone mice attenuates the development of glomerulonephritis although its pathogenic role in the development of lupus nephritis has recently been questioned." (PMID 22761629, 2012). "Still another study, however, revealed comparable TLR9-induced secretion of IgM and IL-10 by PBMCs from lupus patients and healthy donors." (PMID 22952899, 2012).